WASF3 (WASP family member 3)
Description:
Downstream effector molecules involved in the transmission of signals from tyrosine kinase receptors and small GTPases to the actin cytoskeleton. Required for regulation of cell morphology and cytoskeletal organization.
Synonyms: KIAA0900; SCAR3; WAVE3; Brush-1
Tractability: PROTAC: ubiquitination databases record sites on it; its protein half-life has been measured.
Gene: Protein-coding gene on chromosome 13 (26,557,661 to 26,688,948, forward strand). Ensembl gene ENSG00000132970.
Subcellular location: Cytoplasm, cytoskeleton
Pathways (Reactome):
Signal Transduction: RAC1 GTPase cycle; RHO GTPases Activate WASPs and WAVEs; VEGFA-VEGFR2 Pathway
Disease: FCGR3A-mediated phagocytosis
Immune System: Regulation of actin dynamics for phagocytic cup formation
Gene Ontology:
Molecular function: protein binding; Arp2/3 complex binding; protein kinase A regulatory subunit binding; actin binding
Biological process: actin filament polymerization; positive regulation of Arp2/3 complex-mediated actin nucleation; protein-containing complex assembly; actin cytoskeleton organization; modification of postsynaptic actin cytoskeleton
Cellular component: extracellular exosome; lamellipodium; SCAR complex; cytoskeleton; glutamatergic synapse; postsynapse
Genetic constraint (gnomAD): Loss-of-function variants: 9 observed, 43.64 expected, observed/expected ratio (o/e) 0.21, 90% interval 0.12 to 0.36. The upper end of that interval is the gene's LOEUF score, 0.36, which puts it in group 1 of 6, group 1 being the genes least tolerant of losing a copy. Missense variants: 569 observed, 678.19 expected, observed/expected ratio (o/e) 0.84, 90% interval 0.78 to 0.9. Synonymous variants: 238 observed, 260.7 expected, observed/expected ratio (o/e) 0.91, 90% interval 0.82 to 1.02.
Homologues: Orthologues: chimpanzee WASF3 (99% identical), macaque WASF3 (99% identical), rabbit WASF3 (97% identical), dog WASF3 (96% identical), guinea pig WASF3 (95% identical), mouse Wasf3 (94% identical), rat Wasf3 (93% identical), pig WASF3 (92% identical), tropical clawed frog wasf3 (77% identical), zebrafish wasf3b (65% identical), zebrafish wasf3a (58% identical), Drosophila melanogaster SCAR (42% identical), and 1 more. Paralogues in human: WASF1 (49% identical), WASF2 (49% identical).
Diseases named in the same sentence as WASF3 in open-access papers:
WASF3 is named in the same sentence as 36 diseases in open-access papers, as found by Europe PMC text mining. Sharing a sentence is not in itself a finding about the gene and the disease. The quoted sentences say what the papers report.
breast carcinoma (39 papers, 2010 to 2025). "The WASF3 gene has been linked to promoting metastasis in breast cancer (BC) cells, and low expression reduces invasion potential." (PMID 38125536, 2023). "The set of selected genes was composed of a group of angiogenesis-related genes (VEGF, PDGF, ANG-1, and PF-4) and genes that have been previously associated with carcinogenic or metastatic processes in breast cancer (WASF3, LAPTM4B, TPM3, and TAC1)." (PMID 37176055, 2023). "In various human cancers, like colon, prostate, and pancreatic, however, WASF3 is upregulated and, in the case of breast cancer, linked to increased invasive and metastatic cell potential through the regulation of epithelial-to-mesenchymal transition (EMT)." (PMID 33467681, 2021). "Given that our previous studies have demonstrated WASF3 to be the most closely associated with breast cancer invasion and metastasis of the WASF family members, we subsequently focused our attention on the regulation of WASF3 by SHOX2." (PMID 34465361, 2021). "WASF3, and its family members, are involved in actin cytoskeleton reorganization and high level expression has been associated with invasion in breast cancer cells." (PMID 20717117, 2010). "For instance, enhanced levels of WASF3 gene expression could promote cancer cell invasiveness and are associated with the highly aggressive breast cancer subtypes." (PMID 34967509, 2022). "Recently, however, a Wasf3 null mouse model introduced to the polyoma middle-T antigen (PyMT) has been successfully generated to evaluate the effects of Wasf3 loss in a spontaneous model of breast cancer metastasis." (PMID 33467681, 2021). "The WASF3 gene promotes the invasion and metastasis of breast cancer cells that have undergone epithelial-to-mesenchymal transition, making it a potential target for inhibiting breast cancer cell infiltration and metastasis." (PMID 40564276, 2025). "The inactivation of WASF3 in both breast cancer and prostate cancer cells can result in reduced cell migration and invasion." (PMID 38625593, 2025). "In this context, STAT3 collaborates with SHOX2 to form a functional immunocomplex, thereby enhancing the transcriptional activity of WASF3 in breast cancer cells and promoting breast cancer metastasis." (PMID 38429660, 2024). "In conclusion, our study elucidates the impact of WASF3 overexpression on breast cancer progression through intricate regulatory networks." (PMID 38125536, 2023). "Here, we reveal that SHOX2 signaling additionally influences the metastatic process through WASF3/E-Cadherin signaling in breast cancer cells." (PMID 34465361, 2021). "Specifically, the functional activation of HER2 using NRG was seen to induce the phosphorylation of WASF3 in HER2-positive SKBR3 breast cancer cells." (PMID 33467681, 2021). "The data presented here provide the first evidence that the transcriptional activation of WASF3 is synergistically regulated by SHOX2 and STAT3 through their assembly of a functional complex on the WASF3 promoter in breast cancer cells." (PMID 34465361, 2021). "The results of this study suggest that SHOX2 cooperates with STAT3 to drive breast cancer metastasis through upregulating the metastasis-promoting gene WASF3." (PMID 34465361, 2021). "A previous study showed that the WASF3 gene is a promoter of cell invasion in breast cancer and the Nckap1 can keep WASF3 in an inactive conformation through binding to the WASF homology domain at the N-terminus." (PMID 34917619, 2021). "This was confirmed in a study showing that the overexpression of miR-31 synthetic precursors leads to a decrease in WASF3 expression and protein levels in breast cancer cells." (PMID 33467681, 2021).
breast carcinoma (continued). "We further demonstrated that STAT3 cooperates with SHOX2 to form a functional immunocomplex on the WASF3 promoter to promote WASF3 transcriptional activity in breast cancer cells." (PMID 34465361, 2021). "Here, we show for the first time that SHOX2 drives breast cancer metastasis through the regulation of Wiskott-Aldridge Syndrome (WAS) protein family member 3 (WASF3), an actin cytoskeleton controlling and metastasis-promoting gene." (PMID 34465361, 2021). "The forced expression of WASF3 in vitro, however, was seen to override miR-93’s ability to suppress breast cancer invasion." (PMID 33467681, 2021). "Overexpression of NCKAP1 also increased the invasion potential of breast cancer cells, in addition to the levels of Rac1 in the WASF3 immunocomplex, suggesting NCKAP1 acts to enhances Rac1 engagement." (PMID 33467681, 2021). "miR-10b, 373, and 520c are examples of metastasis promoting miRNAs and are seen to be upregulated in WASF3 overexpressing T47D breast cancer cells." (PMID 33467681, 2021). "In contrast, these levels were seen to increase following the overexpressing KRASG12V and even further following the concurrent overexpression of WASF3 in T47D breast cancer cells." (PMID 33467681, 2021). "It appears that E-Cadherin is one of the downstream targets of WASF3 in breast cancer cells and impaired invasion of ATAD3A knockdown cells can be rescued by restoring WASF3 protein function." (PMID 33113782, 2020). "Our recent study demonstrates that ATAD3A regulates the invasion and metastatic potential of breast cancer cells through interacting with Wiskott–Aldridge syndrome family protein 3 (WASF3)." (PMID 33113782, 2020). "In particular, overexpression of ATAD3A advances breast cancer metastasis by increasing the stability of WASF3 protein, a well-studied tumor metastasis promoter." (PMID 33113782, 2020). "ATAD3A is a novel interacting partner of WASF3 and acts as a crucial mediator to promote cell invasion in breast cancer by regulating the stabilization of WASF3 with the ER protein GPR78, a resident chaperone involved in protein degradation." (PMID 33113782, 2020). "WASF3 is a tumor metastasis driver in breast cancer, and its knockdown leads to a significant reduction in metastatic breast cancer cell invasion and metastasis in mice." (PMID 30867003, 2019). "For instance, miR-200 was shown to target cytoskeleton remodeling proteins in breast cancer cells, including WASF3, Moesin, FHOD1, PPM1F, WIPF1 and Cofilin2, functional mediators of miR-200 in the suppression of invasion and/or metastasis." (PMID 26334393, 2015). "Downregulation of WASF3 has been found to inhibit the invasion and metastasis of breast cancer cells, and has been proposed as a metastasis promoter gene." (PMID 25120680, 2014). "The demonstration that WASF3 promotes metastasis in prostate cancer cells, extends the previous observations for a single breast cancer cell line, MDA-MB-231, although the lung metastasis assay is less robust for prostate cancer cells." (PMID 20717117, 2010). "This gene was also shown to be related to unfavorable distant metastasis-free survival and could promote WASF3 transcriptional activity to induce the growth and metastasis of breast cancer." (PMID 38561388, 2024). "In our study, we found an association of WASF3 and some other WAVE complex components (that are part of the prognostic signature) with invasive breast cancer that molecular pattern is associated with aggressive (basal‐like) breast cancer subtype." (PMID 34967509, 2022). "The ATPase family AAA domain-containing protein 3 (ATAD3) proteins (ATAD3A and ATAD3B) regulate MAMs by interacting with GRP78/BiP-Wiskoff-Aldrich syndrome protein family member 3 (WASF3) complex, in which WASF3 acts as a bridge and has been identified in breast cancer cells." (PMID 35733995, 2022).
breast carcinoma (continued). "Nevertheless, our study underscores the complexity of WASF3 transcriptional activation and provides evidence that SHOX2 and STAT3 are assembled in the same complex on the WASF3 promoter and act synergistically to promote WASF3 expression in breast cancer cells." (PMID 34465361, 2021). "The transcriptional regulation of WASF3 by SHOX2 encouraged us to determine whether WASF3 was a functional downstream target of SHOX2 during its promotion of breast cancer metastasis." (PMID 34465361, 2021). "Among them, WASF3 is a well-characterized protein controlling breast cancer metastasis." (PMID 30867003, 2019). "However, recent studies also demonstrate potential tumor suppressor function of Wasf3 upon overexpression in PyMT breast cancer cells thus indicating heterogeneity of WAVE3‐based complex signaling through differential effect on actin cytoskeleton and cell proliferation." (PMID 34967509, 2022). "Thus, the downregulation of NCKAP1 inhibits the activity of WASF3 and may suppresses metastasis in breast cancer cells." (PMID 34917619, 2021). "ATAD3A increases breast cancer metastasis through metastasis promoter WASF3, and knockdown of ATAD3A can inhibit the migration of colon cancer cells and breast cancer cells." (PMID 38018291, 2023). "It was observed that protein interaction combinations of WASF3 with some members of WAVE complex and RAC1 are responsible for breast cancer aggressiveness and metastasis." (PMID 34967509, 2022). "The levels of WASF3 protein increased significantly in MDA-MB-231 and MCF7 breast cancer cells incubated under hypoxic conditions." (PMID 33467681, 2021). "In breast cancer cells, SHOX2 directly activates Wiskott-Aldridge syndrome protein family member 3 (WASF3), a metastasis-promoting gene, at the transcriptional level, leading to a significant increase in metastatic potential." (PMID 34465361, 2021). "Our previous study has shown that knockdown of WASF3 upregulates KISS1, a metastasis suppressor, with concomitant reduced invasion and MMP9 activity in breast cancer cells." (PMID 30867003, 2019). "Our previous studies further demonstrated that NAP1 is required for the protein stability of WASF3 in breast cancer cells, implicating that NAP1 is a critical regulator in favor of breast cancer metastasis." (PMID 30867003, 2019). "Although a high SHOX-2 expression was correlated to enhanced migration and invasion capacities for breast cancer cells through a SHOX-2/STAT3/WASF3 axis, no relation has been established between the SHOX-2 expression and fibrinolysis." (PMID 35935486, 2022). "While MDA-MB-231, MDA-MB-435, and BT549 breast cancer cell lines demonstrated high levels of WASF3 and low levels of miR-31, the reverse was seen in non-metastatic T47D and MCF7 cell lines (low WASF3, high miR-31)." (PMID 33467681, 2021). "In this analysis, SHOX2 expression levels were found to be significantly correlated with the expression of two WASF genes, WASF1 and WASF3, suggesting SHOX2 may promote breast cancer metastasis through WASF-mediated signaling." (PMID 34465361, 2021). "Mechanistically, SHOX2 activates signal transducer and activator of transcription 3 (STAT3) and recruits it to the WASF3 promoter, where STAT3 cooperates with SHOX2 to form a functional immunocomplex to promote WASF3 transcriptional activity in breast cancer cells." (PMID 34465361, 2021). "A recent study showed that miR-200c could inhibit EMT in breast cancer through the increase of E-cadherin, and WAS Protein Family Member 3 (WASF3) could inhibit miR-200c expression." (PMID 32231566, 2020). "To investigate whether the specific binding of SHOX2 to the WASF3 promoter was required for the transcriptional activation of WASF3, we carried out ChIP assays which demonstrated the specific occupancy of SHOX2 at the WASF3 promoter-binding sites in breast cancer cells." (PMID 34465361, 2021).
breast carcinoma (continued). "We have demonstrated previously that, unlike WASF3, WASF1 is not required for the invasion and metastasis of breast cancer cells." (PMID 34465361, 2021).
prostate carcinoma (9 papers, 2010 to 2025). A carcinoma that arises from epithelial cells of the prostate gland. "In contrast, deletion of WASF3 in breast and prostate cancer cells leads to a loss of motility, invasion, and metastasis, partly related to the reduced ability to generate lamellipodia." (PMID 37176055, 2023). "To evaluate the consequences of loss of WASF3 protein expression in prostate cancer cells, we subjected them to matrigel invasion assays." (PMID 20717117, 2010). "The WASF3 protein is involved in cell movement and invasion, and to investigate its role in prostate cancer progression we studied the phenotypic effects of knockdown in primary tumors and cell lines." (PMID 20717117, 2010). "Overall, these observations demonstrate a critical role for WASF3 in the progression of prostate cancer and identify a potential target to control tumorigenicity and metastasis." (PMID 20717117, 2010). "Immunohistochemical analysis of high-grade human prostate cancer demonstrated increased levels of WASF3 compared with normal prostate epithelium." (PMID 20717117, 2010). "We, therefore, initiated a series of experiments to analyze the role of WASF3 expression in prostate cancer metastasis." (PMID 20717117, 2010). "During our overall survey of WASF3 expression in tumor cells, high levels were noted in prostate cancer cells and we now demonstrate that cells from high-grade tumors show increased WASF3 expression." (PMID 20717117, 2010). "To evaluate the role of WASF3 in anchorage independent growth, we seeded prostate cancer cells in soft agar and evaluated colony size and number." (PMID 20717117, 2010). "WASF3, another enriched gene in ABC 1 from eMS and MS, encodes an actin-binding protein that regulates cytoskeletal morphology and promotes cellular metastasis and invasion in breast and prostate cancer." (PMID 40359016, 2025). "Interestingly, an increase in phosphoactivated WASF3 and WASF3 protein levels was observed in prostate cancer DU145 cells following the treatment of IL-6." (PMID 33467681, 2021). "In addition, it has been reported that, compared with lower stage tumors and normal tissue, WASF3 expression is increased in advanced breast and prostate cancer." (PMID 25120680, 2014). "A role of c-Abl in prostate cancer progression has been demonstrated due to its ability to phosphorylate a Wiskott-Aldrich syndrome protein family, member 3 (WASF3), a protein that controls cellular motility and invasion and is upregulated in advanced metastatic PCa." (PMID 24223753, 2013). "In this report we demonstrate the powerful influence of the WASF3 gene on prostate cancer cell invasion and metastasis suggesting that its up-regulation in advanced stage human prostate cancer may offer a significant target." (PMID 20717117, 2010). "These in vitro data clearly demonstrate that WASF3 can influence phenotypes related to tumor motility and invasion, suggesting that it may influence prostate cancer cell metastasis." (PMID 20717117, 2010). "To investigate whether knockdown of WASF3 could affect metastasis of prostate cancer cells in vivo, as predicted from the invasion assays, we subjected selected clones to an experimental metastasis assay." (PMID 20717117, 2010). "In addition, the present data demonstrated that WASF3 expression was significantly correlated with the histological subtype and tumor staging, which is consistent with previous studies regarding breast and prostate cancer." (PMID 25120680, 2014). "A survey of prostate cancer cell lines using qRT–PCR demonstrated that PC3 and DU145 cells expressed readily detectable levels of WASF3, which correlated with protein levels as assessed using western blotting." (PMID 20717117, 2010). "Thus, to investigate the consequences of inactivation of WASF3 in these prostate cancer cell lines, we created stable clones from PC3 and DU145 cells carrying shRNAs targeting WASF3." (PMID 20717117, 2010).
colon cancer (5 papers, 2014 to 2023). "In colon cancer cell lines, WASF3 and KRASG12V expression likewise increased AKT phosphorylation levels, as well as cell invasion." (PMID 33467681, 2021). "Furthermore, recent studies have reported on the critical role of WASF3 in numerous malignancies, including prostate, breast and colon cancer." (PMID 25120680, 2014). "In breast and colon cancer, ATAD3A forms and stabilizes WASF3 in a complex with endoplasmic protein GRP78." (PMID 31248089, 2019).
gastric cancer (4 papers, 2019 to 2025). A primary or metastatic malignant neoplasm involving the stomach. "Reports have indicated that WASF3 expression is associated with poor prognosis and is a potential prognostic factor for gastric cancer patients, therefore, targeting WASF3 is a novel potential therapeutic strategy for gastric cancer." (PMID 34336682, 2021). "This is because WASF3 regulates actin cytoskeleton organization and cell migration, which are essential for tumor invasion and metastasis, and its overexpression has been linked to poor prognosis in various types of cancer, including breast, lung, and gastric cancer." (PMID 38125536, 2023). "WASF3 expression has been reported to have positive correlation with poor prognosis in stomach cancer patients." (PMID 38954213, 2025).
lymph node metastases (2 papers, 2012 to 2014). "Notably, the protein expression of WASF3 was not significantly increased in patients with lymph node metastases when compared with those without lymph node metastases." (PMID 25120680, 2014).